EZH2 (enhancer of zeste 2 polycomb repressive complex 2 subunit)
Diseases named in the same sentence as EZH2 in open-access papers (continued):
Sharing a sentence is not in itself a finding about the gene and the disease.
breast cancer (continued). "This is the first report to describe EZH2 expression in canine mammary tumors." (PMID 27502594, 2016). "In particular, the methyltransferase EZH2/KMT6A and its end-product H3K27me3 mark are found elevated in aggressive breast cancer subtypes, including triple negative and ERα-positive tumors resistant to endocrine therapies, suggesting inactivation of tumor suppressor genes." (PMID 27764788, 2016). "In addition, EZH2 has been reported to be an adverse prognostic marker for breast cancer and an index of an unfavorable tamoxifen outcome." (PMID 27502594, 2016). "For example, the expression level of histone lysine methyltransferase EZH2 which mainly catalyze H3K27me3 is higher in the breast cancer, prostate cancer and bladder cancer, and has been used as a prognostic marker in breast cancer and metastatic prostate cancer." (PMID 27144429, 2016). "We checked the gene expression levels of MCL-1, MTDH, and EZH2 which are proven targets of miR-26a in breast cancer and could be responsible of its anti-proliferative effect." (PMID 27517917, 2016). "Increased EZH2 expression was initially demonstrated in prostate and breast cancer based on microarray studies which supported the hypothesis that the upregulation of this protein is associated with advanced stage and poor prognosis." (PMID 27793053, 2016). "In conclusion, the current evidence suggests that high EZH2 expression may be a promising prognostic factor to human cancers, especially the breast cancer." (PMID 26683709, 2016). "Interestingly, in breast cancer EZH2 interacts with estrogen receptor (ER) and α and β-catenin promoting the expression of ER and Wnt signaling target genes." (PMID 27793053, 2016). "This may partly explain the reason why high EZH2 expression was correlated with poor OS in breast cancer." (PMID 26683709, 2016). "We were interested in determining whether EZH2 is dysregulated in CMTs, which are similar to human breast cancers." (PMID 27502594, 2016). "In our present study, we were interested in determining whether EZH2 is increased in canine mammary tumors, which show similarities to human breast cancer." (PMID 27502594, 2016). "We found that EZH2 is overexpressed in clinical samples of canine mammary carcinomas." (PMID 27502594, 2016). "In addition, EZH2 is also involved in the progression of prostate and breast cancer, which can serve as a marker of aggressive cancer types to predict clinical outcome." (PMID 26484567, 2015). "To further investigate how NBAT1 up-regulated DKK1 via EZH2 in breast cancer, we applied chromatin immunoprecipitation (ChIP)-quantitative real-time PCR (ChIP-qPCR) to analyze trimethylation of histone H3 lysine 27 (H3K27me3) status at DKK1 gene, which is a marker of suppressed chromatin." (PMID 26378045, 2015). "Finally, inactivation of EZH2 in a prototypical human breast cancer cell line promotes in vitro invasion and in vivo tumor growth." (PMID 26637281, 2015). "In addition, expression of EZH2 was induced in response to inhibition of MAPK pathway in human breast cancer cells." (PMID 25955299, 2015). "Furthermore, although EZH2 methylates H3K27 and is associated with breast cancer progression, the disposition of both factors occurs independently in mammary neoplasia." (PMID 26029238, 2015). "Notably, our analysis validated that EZH2 exhibits significantly higher expression in basal-like breast cancer, consistent with previous results." (PMID 25537518, 2015). "We present evidence indicating that high expression of EZH2 is a consequence rather than a cause of cancer and that, in breast cancer, disruption of the PRC2 machinery is likely to promote tumor development." (PMID 26637281, 2015). "EZH2 (enhancer of zeste homologue 2) is a subunit of the polycomb-repressive complex 2 (PRC2) and its overexpression is also associated with the presence of metastasis and poor survival in breast cancer patients." (PMID 25531315, 2015).
breast cancer (continued). "In order to test whether NBAT1 regulates EZH2 functions, we then applied EZH2 inhibitors EI1 or GSK343 in MDA-MB-231 breast cancer cells with NBAT1 over-expression." (PMID 26378045, 2015). "Also, curcumin inhibited EZH2 expression through stimulation of MAPK pathway including SAPK/JNK in human breast cancer cells." (PMID 26362062, 2015). "They further revealed that targeting EZH2 downstream activation pathways such as RAF1-ERK signaling with the MEK inhibitor AZD6244 could prevent breast cancer progression by eliminating CSCs." (PMID 25051981, 2014). "Indeed, overexpression of EZH2 was shown to correlate with breast cancer aggressiveness and poor patient prognosis and the PRC2 complex is up-regulated in breast cancer lymph node metastasis compared to primary tumors." (PMID 24742605, 2014). "EZH2 was found to activate c-Myc in breast cancer cells through the ERα and the Wnt pathways." (PMID 25250015, 2014). "It would be of interest to determine which sites are bound by both PR and EZH2 in normal mammary gland and in breast cancer cells by the use of genome-wide approaches, potentially allowing the identification of target genes repressed by PR in an EZH2-dependent manner." (PMID 25479686, 2014). "Additionally, it has been recently found that methyltransferase EZH2, which is a component of Polycomb repressive complex 2, is O-GlcNAcylated at Ser75 in breast cancer cells." (PMID 25250015, 2014). "In comparison to CD133low cells, CD133high cells also express higher levels of AdoHcyase, known to play a key role in the control of methylation and that, in breast cancer, seems to be involved in regulation of histone methylation via the 2 member enhancer of zeste homolog 2 (EZH2)." (PMID 24330829, 2013). "Using breast cancer and glioblastoma as examples to examine intrinsic subtypes of particular cancers, EZH2 activation was highest in luminal breast cancers and proneural glioblastomas, while HDAC4 activation was highest in basal breast cancer and mesenchymal glioblastoma." (PMID 24079712, 2013). "Interestingly, miR-200b reportedly targets another PRC2 subunit, SUZ12, in breast cancer stem cells, suggesting a possible feedback loop between EZH2 overexpression and miRNA silencing in cancer." (PMID 24348513, 2013). "Overall, these results confirm the role of EZH2 in promoting breast cancer tumorigenesis." (PMID 23826629, 2013). "In this study, we propose that all ILCs or lobular carcinomas in situ showed EZH2 overexpression." (PMID 24266940, 2013). "Given the connection between EZH2 and E-cadherin in the process of breast cancer lymph node metastasis, EZH2 could be an appealing therapeutic target for the treatment of breast cancer metastasis." (PMID 23251464, 2012). "Indeed, transcriptional silencing by CpG island methylation and H3K27me3 mediated by EZH2 have been reported in breast cancer and ATL leukemia." (PMID 22948084, 2012). "In order to determine if all three lncRNA HOTAIR, ncHoxA1, and ncHoxD4 co-express with EZH2, and to help determine the roles of both the lncRNA and Polycomb protein in breast carcinoma, EZH2 protein immunohistochemical staining was performed on the breast carcinoma microarrays." (PMID 23133536, 2012). "Moreover, polycomb proteins such as EZH2 are involved in stem cell maintenance, in line with findings that basal-like breast cancer has a more stem cell-like phenotype." (PMID 20565864, 2010). "Vice versa, inhibition of EZH2 expression by antisense constructs or RNA interference (RNAi) resulted in growth inhibition of cancer cells, and induced anoikis in circulating prostate carcinoma precursor cells or apoptotic cell death in breast cancer cells." (PMID 20920340, 2010). "Increased EZH2 expression in tumorous versus corresponding normal tissue has been also reported for other cancers as well, including malignant melanoma, prostate carcinoma, breast cancer and hepatocellular carcinoma." (PMID 20920340, 2010).
breast cancer (continued). "To determine whether the increased EZH2 levels are functionally relevant in the BRCA1-deficient tumor cells, we made use of cell lines that were derived from KB1P and KP mouse mammary tumors." (PMID 19709408, 2009). "We predict that breast cancer patients with higher EZH2 and lower CDKN1C might receive the greatest benefit from cancer therapeutic targeting of EZH2-mediated gene repression." (PMID 19340297, 2009). "EZH2, another key Polycomb repressor complex 2 component, undergoes gene amplification in several tumor types and is overexpressed in prostate cancer and breast cancer." (PMID 19250546, 2009). "Furthermore, we show that breast cancer expressing both higher EZH2 and lower CDKN1C show a much poorer disease-free survival rate (P = 0.001046) compared to patients with lower EZH2 and higher CDKN1C." (PMID 19340297, 2009). "In addition, a chemical inhibitor of EZH2, 3-deazaneplanocin A (DZNep), is about 20-fold more effective in killing BRCA1-deficient cells compared to BRCA1-proficient mammary tumor cells." (PMID 19709408, 2009). "Hence, it seems unlikely that involvement of EZH2 in ER-signaling contributes greatly to an oncogenic role of EZH2 in breast cancer." (PMID 19099573, 2008). "Interestingly, although EZH2 overexpression correlates with a poor prognosis in breast cancer, BMI1 overexpression correlates with a good outcome." (PMID 19099573, 2008). "Moreover, EZH2 was found to colocalize with USP30-AS1 in the nucleus of breast cancer cells." (PMID 41492473, 2026). "Furthermore, the removal of the PRC2/EZH2 complex in a mouse model of EZH2-overexpressing breast cancer can inhibit cancer proliferation, supporting the notion that EZH2 may influence cancer proliferation." (PMID 40308579, 2025). "Notably, only EZH2 showed higher expression in TNBC groups than other breast cancer subtypes." (PMID 41413688, 2025). "However, EZH2 can behave also oppositely in the regulation of NF-kB target gene expression, depending on the cellular context, as the same authors provided evidence that in the ER-positive luminal-like breast cancer cells, EZH2 negatively regulated NF-kB target genes." (PMID 39769907, 2024). "Previous studies have been reported that histone deacetylase inhibitors or EZH2 inhibitors could result in a phenotypic switch from BLBC into ER+ breast cancer, leading to the acquisition of sensitivity to hormone therapy, but the master regulator remained unclear." (PMID 38491910, 2024). "This may contribute to the suboptimal efficacy of EZH2 inhibitors in breast cancer treatment." (PMID 39080807, 2024). "Furthermore, phosphorylation of EZH2 can mediate its subcellular localization and function, and cytoplasmic pEZH2-T367 enhances breast cancer invasion; in breast cancer cells, p38 phosphorylates EZH2 at T367 to induce EZH2 cytoplasmic localization and binding to vinculin, thereby promoting invasion." (PMID 39409910, 2024). "Enhancer of zeste homolog 2 (EZH2), which is a histone H3 (trimethylation of H3 on lysine 27 (H3K27me3)) methyltransferase, is often overexpressed in a number of solid tumors, such as prostate cancer, breast cancer, colorectal cancer (CRC), melanoma, endometrial cancer, and glioblastoma (GBM)." (PMID 38911968, 2024). "Similarly to the case of an inverse correlation between oncogenic EZH2 and tumor-suppressive RORα in breast cancer, we speculate that the potential oncogenic function of G9a might be augmented by the degradation of FOXO1, which is a known tumor suppressor." (PMID 36639369, 2023). "GBM, LIHC, LUAD, and breast cancer had higher phosphorylation degrees in the T487 locus of EZH2 protein compared with normal tissues, suggesting that protein phosphorylation of EZH2 at the T487 site might function as a promoter in the development and progression of these cancers." (PMID 36545914, 2023). "Hence, degradation of EZH2 could attenuate breast cancer invasion and metastasis in MCF-7 and MDA-MB-231 cells." (PMID 37803297, 2023).
breast cancer (continued). "In addition, pEZH2-T367 induces EZH2 cytoplasmic localization to promote breast cancer metastasis." (PMID 37803297, 2023). "EZH2 also negatively regulates the transcription of the metastasis suppressor gene RKIP in breast and prostate cancer by regulating H3K27 and H3K9-me3 modifications, leading to negative association of EZH2 expression with relapse-free survival in breast cancer." (PMID 37369946, 2023). "Furthermore, extensive studies demonstrated that EZH2 could increase cancer proliferation, angiogenesis and invasion in different malignancies, including breast cancer, melanoma and oral squamous cell carcinoma among others." (PMID 37941056, 2023). "Although the role of EZH2 is context dependent, a substantial amount of the literature on preclinical models suggests that targeting EZH2 in combination with cisplatin chemotherapy could have beneficial effects in the treatment of lung, ovarian, and breast cancers." (PMID 36230683, 2022). "Furthermore, it has not been determined if specific EZH2 genetic variants are associated with breast cancer risk." (PMID 35813302, 2022). "Interestingly, the levels of EZH2 and RORα were inversely correlated in breast cancer, implying that EZH2 might play an oncogenic role by inhibiting RORα-mediated tumor suppression." (PMID 36076977, 2022). "In summary, these results indicate that histone modification participates in the regulation of PDK1 by inhibiting miR-148a, and the existence of the HDAC2/EZH2/miR-148a/PDK1 regulatory axis may be important in breast cancer development and therapeutic resistance." (PMID 35892859, 2022). "Therefore, we focused on exploring the role of EZH2 inhibitors in TAMs differentiation in this study, which may influence the efficacy of EZH2 inhibitors against breast cancer." (PMID 36038549, 2022). "Inhibition of CCL2 could break this loop and reverse the enhanced BC cell tumor proliferation and migration caused by EZH2 inhibitors, which suggested that combinational inhibition of CCL2 with EZH2 inhibitors may be beneficial to the treatment of breast cancer." (PMID 36038549, 2022). "In vivo experimental results showed that EZH2 could promote breast cancer metastasis through CCF." (PMID 35163710, 2022). "Moreover, the level of EZH2 was gradually increased in breast cancer progression scenarios ranging from normal epithelium to epithelial hyperplasia, DCIS, IDC, and distant metastasis; and the expression of EZH2 was an independent predictor of breast cancer recurrence." (PMID 36185256, 2022). "Our study revealed the cooperation between EZH2 and TGFβ signaling in promoting bone metastasis of breast cancer through a methyltransferase-independent mechanism, and demonstrated that targeting FAK may be an effective strategy for treatment of EZH2-induced breast cancer bone metastasis." (PMID 35538070, 2022). "Notably, in breast cancer, EZH2 has been found to be upregulated and promoted the EMT process." (PMID 36185256, 2022). "Therefore, the EZH2–CCF–cGAS axis can be targeted in breast cancer metastasis, and new targets of this pathway may be potential therapeutic strategies to inhibit breast cancer metastasis." (PMID 35163710, 2022). "Hence, we further investigated whether SNHG1 was an epigenetic suppressor of miR-381 via recruiting EZH2 in breast cancer cells." (PMID 34806925, 2021). "Therefore, EZH2 was capabled of promoting proliferation and migration of breast cancer cells." (PMID 34335938, 2021). "And in the study of DZNep’s role on mice airway smooth muscle cells and human basal-like breast cancer cells, the NF-κB nuclear translocation was promoted via the IκB phosphorylation, which credited to the upregulated transcription of Foxc1 after the inhibition of EZH2 and subsequent H3K27me3." (PMID 34930462, 2021). "Therefore, whether EZH2 takes part in the cancer-promoting role of STAT3 in breast cancer remains to be clarified." (PMID 34335938, 2021).
breast cancer (continued). "Therefore, we wondered whether PRMT1-mediated EZH2 methylation is able to promote breast cancer cell proliferation and tumorigenesis." (PMID 34775498, 2021). "The understanding of molecular mechanisms underlying the EZH2-miR-29b/miR-30d-LOXL4 axis affords a novel insight in diagnosis, prognosis, and molecularly targeted therapy of breast cancer and may provide a novel therapeutic approach for breast cancer treatment in the clinic." (PMID 32754259, 2020). "Indeed, while some studies argue for a role of O-GlcNAcylation in the regulation of EZH2 stability and catalytic activity, others propose that the glycosylation rather regulates EZH2 recruitment to some of its target genes such as FOXC1 in breast cancer cells or IL-15 in muscle." (PMID 33126652, 2020). "The results implied that EZH2 might regulate the progression of breast cancer through LOXL4." (PMID 32754259, 2020). "To date, how EZH2 regulates LOXL4 in the progression of breast cancer remains unclear." (PMID 32754259, 2020). "To date, how EZH2 regulates the ECM in the progression of breast cancer remains unknown." (PMID 32754259, 2020). "Given that EZH2-miR-29b/miR-30d-LOXL4 signaling pathway was associated with tumor progression, we next asked whether the expression of these genes was associated with poor prognosis in breast cancer patients." (PMID 32754259, 2020). "It remains unclear how EZH2 regulates ECM remodeling in the progression of breast cancer." (PMID 32754259, 2020). "In agreement with a previous report that BRCA1 acts as a pivotal suppressor of EZH2 in the PRC2 complex 42, it has been shown recently that EZH2 represses expression of FOXO3, but this regulation only occurs when EZH2 becomes hyperactivated in BRCA1-deficient breast cancer cells." (PMID 31410199, 2019). "EZH2 plays crucial role in breast cancer progression through its target genes as identified in this study, thereby signifying that EZH2 target genes may provide a more stringent method of targeting EZH2." (PMID 30760814, 2019). "However, in all cases reduction of EZH2 by miRNAs inhibited tumor growth and metastasis in mouse models, suggesting that these miRNAs act as tumor and metastasis suppressors, and demonstrate that EZH2 is an important therapeutic target in breast cancer." (PMID 31252590, 2019). "Therefore, we concluded that the polymorphisms of EZH2 may influence H3K27 methylation so as to function in the occurrence and prognosis of breast cancer." (PMID 29089464, 2018). "The interaction of H19 with the EZH2-centered regulation has been previously demonstrated in bladder carcinoma, where a mechanism analogous to the one hypothesized in this paper was proposed, and in ERα-positive breast cancer, contributing to chemoresistance." (PMID 29643989, 2018). "EZH2 rs12670401 and rs6464926 polymorphisms, EZH2 and SMYD3 expression, clinical staging, lymph node metastasis, human epidermal growth factor receptor-2 (HER2) status, and metastasis may be correlated with breast cancer susceptibility and prognosis." (PMID 29089464, 2018). "High levels of Ezh2 may not be sufficient to induce mammary tumors in mice, suggesting additional driver mutations are required." (PMID 30080881, 2018). "However, how EZH2 drives metastasis despite the low H3K27me3 levels observed in ER- breast cancer is unknown." (PMID 30022044, 2018). "It was demonstrated recently that in breast cancer, EzH2 promotes a constitutive activation of NF-κB that leads to an increase in its target genes expression, including IL-8, IL-6 and TNF-α cytokines, suggesting that it might be doing the same in our model of CAC." (PMID 29285251, 2017). "Therefore, EZH2 may represent a potential therapeutic target for this aggressive breast cancer, especially for those with a high Ki-67 expression score, which warrants further investigation." (PMID 28241804, 2017).